ZNF564 (zinc finger protein 564)
Description:
May be involved in transcriptional regulation.
Synonyms: MGC26914
Tractability: PROTAC: UniProt records ubiquitination sites on it; ubiquitination databases record sites on it.
Gene: Protein-coding gene on chromosome 19 (12,525,373 to 12,551,542, reverse strand). Ensembl gene ENSG00000249709.
Subcellular location: Nucleus
Subcellular location (Human Protein Atlas): Golgi apparatus
Pathways (Reactome):
Gene expression (Transcription): Generic Transcription Pathway
Gene Ontology:
Molecular function: protein binding; DNA-binding transcription factor activity; RNA polymerase II cis-regulatory region sequence-specific DNA binding
Biological process: regulation of transcription by RNA polymerase II; regulation of DNA-templated transcription
Cellular component: nucleus
Genetic constraint (gnomAD): Loss-of-function variants: 5 observed, 11.1 expected, observed/expected ratio (o/e) 0.45, 90% interval 0.23 to 0.95. The upper end of that interval is the gene's LOEUF score, 0.95, which puts it in group 4 of 6, group 1 being the genes least tolerant of losing a copy. Missense variants: 603 observed, 704.14 expected, observed/expected ratio (o/e) 0.86, 90% interval 0.8 to 0.92. Synonymous variants: 242 observed, 228.55 expected, observed/expected ratio (o/e) 1.06, 90% interval 0.95 to 1.18.
Homologues: Orthologues: chimpanzee ZNF564 (99% identical), Drosophila melanogaster CG14442 (5% identical), Drosophila melanogaster CG14440 (2% identical). Paralogues in human: ZNF567 (41% identical), ZNF382 (32% identical), ZNF613 (32% identical), ZNF649 (31% identical), ZNF350 (28% identical), IKZF1 (12% identical), IKZF4 (12% identical), IKZF2 (10% identical), ZNF639 (10% identical), IKZF3 (10% identical), ZNF821 (7% identical).